APLNR (apelin receptor)
Diseases named in the same sentence as APLNR in open-access papers (continued):
Sharing a sentence is not in itself a finding about the gene and the disease.
cancer (49 papers, 2014 to 2025). A tumor composed of atypical neoplastic, often pleomorphic cells that invade other tissues. "It was acknowledged that increased expression of the apelin receptor caused cancer cell relocation and migration to the omentum." (PMID 40076482, 2025). "The APLNR (apelin receptor) has been shown to be an essential gene for cancer immunotherapy, with deficiency in APLNR leading to immunotherapy failure." (PMID 30783205, 2019). "APL could indicate the diagnostic index for the degree of cancer progression, therefore it could serve as a potential biomarker for targeted therapy for cancers and pharmacological blockage via APLNR antagonists." (PMID 38213742, 2024). "Apelin exerts influence on lipid uptake into cancer cells, which is mediated by the apelin receptor (APJ)." (PMID 40076482, 2025). "Our study indicated a new direction for the development of novel APLNR antagonists and also provided an effective strategy for cancer therapy by combining APLNR antagonists with Sunitinib or similar antiangiogenic agents." (PMID 41316451, 2025). "The apelin receptor has also garnered attention as a complex target in various cancers, including GBM." (PMID 38803685, 2024). "In line with this, the palmitylation level of APLNR in the cancer pain model group was higher than that in the sham operation group and positively correlated with the duration of NCP." (PMID 38164190, 2024). "The apelin receptor has emerged as a potential therapeutic target in various cancers, including GBM." (PMID 38803685, 2024). "APLNR was later identified as part of an angiogenic gene signature in more than 1000 different well-vascularized primary human cancer biopsies." (PMID 34359800, 2021). "Although these observations make the Apelin/Apelin receptor pathway a potentially attractive target for anti‐angiogenic cancer therapy, the detailed effects of its targeting for cancer treatment in vivo are poorly understood." (PMID 31267692, 2019). "Alteration of apelin cleavage sites generates apelin-dm peptide that effectively represses the malignant and metastatic phenotype of cancer cells and angiogenesis through modulation of apelin receptor dynamics, affinity, internalization, and diverse apelin signaling pathways." (PMID 39962271, 2025). "Finally, we designed competitive peptides targeting the palmitoylated site of APLNR to treat cancer pain in combination with morphine and achieved good results." (PMID 38164190, 2024). "Therefore, targeting APLNR palmitoylation in combination with morphine is a potent method for cancer pain treatment." (PMID 38164190, 2024). "APLN/APLNR had been showed as prognostic markers in several types of cancers." (PMID 36193059, 2022). "Finally, evidence for the role of APLN/APLNR signaling in adaptive immunity came from a recent study that identified APLNR as one of the genes essential for immunotherapy in cancer." (PMID 34359800, 2021). "APLN/APLNR signaling has key function in several physiological processes like cardiac function, angiogenesis, metabolism and body fluid homeostasis, and also in pathological conditions like heart failure, cancer, obesity and diabetes (reviewed in detail)." (PMID 31690961, 2020). "In addition, somatic mutations in cancer cells, including loss-of-function mutations in JAK1/2, APLNR, PTPN2, and PBRM1, significantly correlate with the efficacy of cancer immunotherapies." (PMID 32244804, 2020). "This opposite effect in comparison to apelin treatment indicated that inhibition of apelin receptor and its downstream signalling may affect the capability of cancer cells to migrate." (PMID 30127323, 2018). "This study provides a novel direction for APLNR antagonist development and demonstrates that combining Candesartan with the standard antiangiogenic agent Sunitinib leverages the advantage of drug repurposing, suggesting a promising and rapidly translatable strategy for optimized cancer therapy." (PMID 41316451, 2025).
cancer (continued). "Consequently, the early identification and prevention of metastasis, whether through traditional treatments or interventions in the apelin/ apelin receptor interaction, emerge as crucial strategies in mitigating cancer-related pathologies and fatalities." (PMID 39962271, 2025). "Most recently, protamine has been identified as an APLNR antagonist, which can explain some of the side effects observed in patients treated with protamine, but this means that anti-angiogenic activity may be used to treat cancer." (PMID 36614283, 2023). "Apelin may play a role in cancer development by activating the apelin receptor, APJ." (PMID 36230579, 2022). "Furthermore, APLNR is a marker of increased angiogenesis in many cancer types." (PMID 32545380, 2020). "Interestingly, apelin receptor antagonists could be promising therapeutic compounds for cancer treatment." (PMID 29875677, 2018). "The apelin receptor is a class A GPCR that binds two endogenous peptide ligands, apelin and ELA, and plays a role in the proliferation and survival of cancer cells." (PMID 38803685, 2024). "A consensus is emerging that pharmacological inhibition of the apelin receptor might offer beneficial effects on survival, either through direct actions on stem cell populations or indirectly through anti-angiogenesis or both, in various forms of cancer, including GBM." (PMID 38803685, 2024). "M3G, the main metabolite of morphine, accumulated in the cancer pain model and activated ERK1/2 signal transduction through APLNR." (PMID 38164190, 2024). "Therefore, targeting APLN/APLNR signalling pathway could be a promising strategy to treat cancer." (PMID 38213742, 2024). "Thus, there is a positive feedback loop for ZDHHC9, ERK1/2, and APLNR in the NCP model that exacerbates pain-induced inflammatory responses and drug resistance in cancer." (PMID 38164190, 2024). "The pathological role of the apelin receptor and its endogenous peptide ligands, apelin and ELA, in cancers such as GBM may well extend beyond angiogenesis." (PMID 38803685, 2024). "Moreover, recent CRISPR/CAS9 screening studies implicated other genes involved in regulating IFNy sensitivity as a cancer immunotherapy target, namely, tyrosine-protein phosphatase non-receptor type 2 (PTPN2) and apelin receptor (APLNR)." (PMID 31196219, 2019).
cardiovascular diseases (32 papers, 2012 to 2024). "The association between rs9943582, a functional variant in the 5’ flanking region (-154G/A) of APLNR, and the incidence of cardiovascular disease has been extensively studied; however, the results have been contradictory." (PMID 32849850, 2020). "Dysfunction of the apelinergic system, comprised of the neuropeptide apelin mediating its effects via the G protein-coupled apelin receptor (APJ), may underlie the onset of cardiovascular disease such as hypertension." (PMID 30459635, 2018). "The apelin (endogenous ligand of APLNR)/APLNR system is involved in various physiological and pathological processes, including cardiovascular disease, angiogenesis, energy metabolism, and humoral homeostasis." (PMID 38164190, 2024). "The APLNR holds significant promise as a therapeutic target for cardiovascular diseases, with the development of novel agonists like WN561 marking a pivotal step forward." (PMID 39648165, 2024). "The apelin receptor is a promising therapeutic target in cardiovascular diseases such as PAH, but is yet to be fully exploited." (PMID 36967803, 2023). "APLN and APLNR are regulated by hypoxia, and the APLN–APLNR axis system has a protective effect on cardiovascular diseases." (PMID 36611783, 2023). "This review will discuss current cardiovascular disease targets of the apelin system and future clinical utility of apelin receptor agonism." (PMID 37956047, 2023). "The apelin/apelin receptor system plays an important role in cardiovascular function, and apelin therapy has beneficial effects in cardiovascular disease." (PMID 33573223, 2021). "The APLN/APLNR signaling pathway is involved in various pathological processes and physiological functions, including cardiovascular disease, angiogenesis, energy metabolism, and central nervous system disease." (PMID 32849850, 2020). "Apelin, an endogenous ligand for Apelin receptor, acts as a key modulator of cardiovascular diseases." (PMID 29245958, 2017). "The results suggest this system may be used for further investigations into the role of the apelin receptor in cardiovascular disease and provides a platform with the potential for high throughput screening of novel therapeutic agents." (PMID 36239923, 2023). "We also demonstrate proof-of-principle that these fluorescent ligands could be used to screen for hits against the apelin receptor in drug discovery pipelines to identify new compounds that may have clinical use in cardiovascular diseases such as PAH." (PMID 36967803, 2023).
metabolic disorders (7 papers, 2019 to 2025). "Apelin-36-[L28A] and apelin-36-[L28C(30kDa-PEG)] are G protein biased ligands of the apelin receptor, suggesting that the apelin receptor is an important therapeutic target in metabolic diseases." (PMID 31472173, 2019). "Several peptides are not yet approved but are under clinical investigation for nonmuscle indications, including apelin (antihypertensive) and the apelin–receptor agonist Elabela (cardioprotective and renoprotective), urocortin I (cardioprotective) and MOTS‐c (metabolic diseases)." (PMID 41231146, 2025).
APLNR also shares sentences with these, for which no sentence is quoted: liver disease (8 papers); melanoma (8); colon adenocarcinoma (7); Cirrhosis (4); Hyperglycemia (4); COVID-19 (3); fibrosis (3); heart diseases (3); infection (3); Infertility (3); liver cancer (3); proliferative diabetic retinopathy (3); psychosis (3); pulmonary fibrosis (3); Sepsis (3); systemic sclerosis (3); acute coronary syndrome (2); adenocarcinoma (2); cardiomyopathy (2); endothelial dysfunction (2); epilepsy (2); Hepatic steatosis (2); injury (2); metastatic disease (2); oral squamous cell carcinoma (2); periodontitis (2); respiratory disease (2); serous ovarian cancer (2); steatosis (2); subarachnoid hemorrhage (2).
A further 54 diseases each share a sentence with APLNR in 1 paper.